Y_RNA (Y RNA )
Gene: Miscellaneous RNA gene on chromosome X (109,744,643 to 109,744,749, reverse strand). Ensembl gene ENSG00000252069.
Homologues: Orthologues: macaque Y_RNA (94% identical). Paralogues in human: Y_RNA (90% identical), RNY1 (89% identical), RNY1P11 (88% identical), Y_RNA (88% identical), Y_RNA (86% identical), Y_RNA (85% identical), Y_RNA (84% identical), RNY1P13 (83% identical), Y_RNA (83% identical), RNY1P10 (82% identical), Y_RNA (82% identical), RNY1P8 (81% identical), and 99 more.